IFNG (interferon gamma)
Diseases named in the same sentence as IFNG in open-access papers (continued):
Sharing a sentence is not in itself a finding about the gene and the disease.
colorectal cancer (continued). "These together suggest that although IFNγ can target colorectal cancer stemness, it may hold true for only a small proportion of sporadic colorectal cancer patients, and additional strategies are needed to enhance the sensitivity of colorectal cancer cells carrying APC mutation to IFNγ treatment." (PMID 37671945, 2023). "In addition to its effects in the gastric body, H. pylori colonization in the mouse intestinal tract has been shown to increase production of c-myc, interleukin-1 (IL-1), IL-6, and tumor necrosis factor (TNF), but reduced interferon-gamma (IFN-γ), with subsequent development of colorectal cancer." (PMID 34360663, 2021). "Survival analysis of core genes suggests that high expression of IFNG, MMP9, and IL1B indicates a shorter survival time in colorectal cancer patients." (PMID 40868987, 2025). "The results indicate that the p-values of survival analysis for core genes IFNG, IL1B, and MMP9 are all less than 0.05, suggesting that in colorectal cancer patients, the high expression of IFNG, MMP9, and IL1B indicates a shorter survival time." (PMID 40868987, 2025). "In colorectal cancer, MMP2, IL1B, IFNG, and CD4 have significant infiltration relationships with many immune cells." (PMID 40868987, 2025). "A notable example is the intratumoral delivery of an engineered E. coli Nissle 1917 strain designed to produce interferon gamma (IFN-γ), which has shown efficacy in a murine model of MC38 colorectal cancer." (PMID 40437288, 2025). "Additionally, we found that interferon-gamma and interleukin-2 receptor subunit β were linked to a reduced risk of CRC, suggesting that therapeutic agents targeting these molecules could be promising options in the treatment of colorectal cancer." (PMID 39612465, 2024). "Here, we used distal T cell receptor (TCR) and IFNγ reporter mice (Nr4a3-Tocky-Ifnγ-YFP) and a colorectal cancer (CRC) model to interrogate T cell activity during BCT with attenuated STm." (PMID 39558103, 2024). "The authors observed increased expression of IL-10 and IL-13 and decreased expression of IL-1β, IL-6, interferon gamma (IFN-γ), TNF-α, IL-12, and IGF-1 in peripheral blood mononuclear cells (PBMCs) derived from patients with colorectal cancer." (PMID 38957737, 2024). "Our further clinical analysis revealed also the antagonist effect between IFNγ and CBX3 in colorectal cancer on STAT1/PD-L1 expression." (PMID 38684864, 2024). "Colorectal cancer (CRC) is another frequent colon pathology and IFNγ signaling plays crucial roles in its development and treatment." (PMID 38684864, 2024). "Given the important role of IFNγ/STAT1/PD-L1 axis in oncogenesis and cancer treatment, targeting the IFNγ signaling pathway as therapy is a rational and novel management in colorectal cancer." (PMID 38684864, 2024). "We then examined clinical data from colorectal cancer (CRC) patients to investigate the potential antagonist effect of CBX3 and IFNγ on the expression of STAT1/PD-L1 in CRC." (PMID 38684864, 2024). "Our results were consistent with a recent study demonstrating that TIGIT expression was inversely correlated with the expression of cytotoxic cytokines, including IFNγ, from CD8+ T cells infiltrating colorectal cancer." (PMID 35053427, 2022). "The aim of the study is to assess expression levels of CPEB4, APC, TRIP13, EIF2S3, EIF4A1, IFNg, PIK3CA and CTNNB1 genes in tumors and peripheral bloods of colorectal cancer patients in stages I–IV." (PMID 33237662, 2021). "Recently, it was shown that GBP1 and GBP4 are IFNG-dependent and were directly co-expressed with CD8A in colorectal cancer." (PMID 34487971, 2021).
colorectal cancer (continued). "The mRNA levels of CPEB4, APC, TRIP13, EIF2S3, EIF4A1, IFNg, PIK3CA and CTNNB1 genes expressed in colorectal cancer tissue specimens, colorectal cancer blood samples, normal colon tissues and blood samples were analysed." (PMID 33237662, 2021). "Previous studies have highlighted that IFNG up-regulates PDL1in a STAT1 dependent manner in gastric and colorectal cancer." (PMID 34566988, 2021). "In cancer, the Gbp family members are among the IFNγ-dependent genes most highly induced in cancer patients, and increased tissue expression of human GBP2 in several cancer types including colorectal cancer is correlated with favorable prognostic outcomes." (PMID 34912335, 2021). "IFNG and HAVCR2 gene expression, which were augmented, best defined Th1-like T cells in colorectal cancer, while PDCD1, an immune checkpoint inhibitor, was decreased." (PMID 31191543, 2019). "By using lung and colorectal cancer models, we showed that LNT treatments inhibited tumor angiogenesis via increased IFNγ production in a T cell-independent manner." (PMID 30373628, 2018). "Healthy colon and peripheral blood was obtained from colorectal cancer (CRC) patients undergoing colonic resection and we assessed glycoprotein B (gB, UL55) and tegument (pp65, UL83) specific IL-10/IFNγ production using fluorospot." (PMID 27926930, 2016). "The infiltrating Th1 cells secrete IFNγ, which, in addition to its immune functions, promotes the release of CXCL10 from IFNγ receptor-expressing colorectal carcinoma cells while up-regulating CXCR3 expression." (PMID 22408433, 2012). "Furthermore, these three genes-TLR2, IFNG, and CD163-are abundantly expressed in colorectal cancer (CRC) tumor tissues." (PMID 41300749, 2025). "Functional assays and lectin microarray analysis using MSI colorectal cancer cell lines revealed that GALNT7 knockdown enhanced IFNγ-induced PD-L1 expression without altering cell-surface glycosylation." (PMID 40824763, 2025). "Our findings indicate that CBX3 could antagonize IFNγ, CBX3 thus becomes a potential target to improve colorectal cancer treatment." (PMID 38684864, 2024). "That is, although IFNγ is not an ideal remedy for treating colorectal cancers, CAP can sensitize tumor cells to IFNγ treatment." (PMID 37671945, 2023). "Accordingly, in mouse models of colorectal cancer (CRC), heterozygous genetic deletion of IFNγ (Ifng+/-), homozygous deletion of the corresponding receptor (Ifngr1-/-), or antibody-mediated neutralisation of IFNγ, increased adenocarcinoma development." (PMID 37455828, 2023). "To determine if an anti-IFNγ immunoPET tracer could identify intratumoral immune activity after ICI, we utilized BALB/c mice bearing subcutaneous CT26 colorectal cancer as a responsive model for combined ICI (anti-CTLA4 and anti-PD-1) therapy." (PMID 38130991, 2023). "Consequently, AJUBA suppresses IFNγ-stimulated STAT1 phosphorylation and translocation, promoting colorectal cancer growth." (PMID 34385592, 2022). "Given that a vast majority of colorectal cancer patients do not have mutations in IFNγ signaling genes, it is unlikely that this represents a major contribution to ICB resistance in colorectal cancer patients." (PMID 34385592, 2022). "Elevated concentrations of IL-8, TNFα, IL-12 (a heterodimer consisting of IL-12p40 and IL-12p70), GMCSF, and IFNγ in blood have been reported in colorectal cancer patients in some but not all studies." (PMID 20924374, 2010). "Altogether, this work identifies a new antagonist interplay between CBX3 and IFNγ signaling to regulate colon immune response and chemosensitivity of colorectal cancer, which highlights CBX3 as a potential target to improve the treatment of UC and colorectal cancer." (PMID 38684864, 2024). "We define three types of response to IFNγ in colorectal cancer: strong, weak, and noninducibility." (PMID 37565053, 2023).
colorectal cancer (continued). "Importantly, these results may suggest a beneficial synergy between IFNγ and CAP in treating colorectal cancers and possibly other forms of malignancy as well." (PMID 37671945, 2023). "Augmentation of CD4+ T cells, CD8+ T cells and CD49b+ NK cells, as well as increased expressions of IFNg, IL10, CXCR4, and reduced expressions of IL17, STAT3 screened from gene and protein levels, jointly create a microenvironment conducive to inhibit the progress of colorectal cancer." (PMID 37143538, 2023). "Given this proimmune impact of tsMHC-II expression, one of the immunologic escape mechanisms that colorectal cancer cells might utilize is cell-autonomous transcriptional repression of CIITA and consequent noninducibility of tsMHC-II by IFNγ." (PMID 37565053, 2023).
Allergy (231 papers, 2006 to 2026). An allergy is an immune response or reaction to substances that are usually not harmful. "Th1 lymphocytes produce Interferon-gamma (IFN-γ) while Th2 cells are mainly producers of interleukin 4 (IL-4), IL-5 and IL-13, which is a hallmark of atopy or allergy." (PMID 34063174, 2021). "In particular, the authors found a diminished capacity of cord blood T-cells to produce the Th1 cytokine IFNγ in infants from exposed mothers, which is a risk factor for the development of allergic disease in infancy." (PMID 22047167, 2011). "Cord blood T cells (CBTC) from a proportion of newborns express low/deficient levels of some protein kinase C (PKC) isozymes, with low levels of PKCζ correlating with increased risk of developing allergy and associated decrease in interferon-gamma (IFN-γ) producing T cells." (PMID 34884454, 2021). "Since a cytokine imbalance in the IFNγ/IL4 ratio from iNKT cells is associated with the pathogenesis of allergic diseases, we determined whether repeated α-GalCer activation alters the cytokine profiles of activated iNKT cells from Vα14Tg NC mice." (PMID 34829848, 2021). "Similar cytokine production effects were found with eicosapentaenoic acid (EPA) and arachidonic acid (AA), whereas linoleic acid (LA) increased OX40L surface expression and subsequent T-cell-derived IL-13/IFNγ ratios, suggesting an increased risk of allergy development." (PMID 32431702, 2020). "Furthermore, on the inter-individual level, higher PKCζ expression has been shown to correlate with the capacity of neonatal T-cells to produce more IFNγ upon stimulation and, at the same time, to be associated with a lower risk of allergic disease development in early childhood years." (PMID 28159873, 2017). "IFNγ can contribute to the resolution of allergy‐related responses, and downregulation of Th1 cells has been associated with more severe allergic reaction." (PMID 40635637, 2025). "For example, lactic acid bacteria (LAB) are particularly effective in preventing allergic diseases like atopic eczema in infants by enhancing the body’s capacity to produce immune-enhancing cytokines such as interferon-gamma (IFN-γ)." (PMID 39519539, 2024). "The identification of an immunoregulatory IFNγ-producing B cell population in infected mice provides new insights into the interaction between infection and allergy and, more broadly, immune regulation mechanisms." (PMID 37759658, 2023). "Any disruption of the cytokine secretion, especially increased IL4 and/or decreased IFNG, are considered to be a major factor contributing to allergy development." (PMID 37520545, 2023). "Studies regarding DNA methylation changes in cytokine genes such as interferon gamma (IFN-γ), interleukin-4 (IL-4) and IL-5 and in Forkhead box P3 (FoxP3) indicate that changes in DNA methylation may predispose IgE-mediated food sensitization or allergy in early childhood." (PMID 36756279, 2023). "It was also shown that methylation profile of IL4, IL5, IL10, IFNG and FOXP3 was associated with environmental exposures and the direction of methylation dynamics differed depending on the presence and types of allergy symptoms." (PMID 37520545, 2023). "Complications during pregnancy were linked to different pattern of the IFNG, IL5, IL4 and IL10 methylation depending on allergy status." (PMID 37520545, 2023). "Possible explanation indicate that endotoxin is a potent inducer of interleukin-12 and interferon gamma, which downregulate the production of T-lymphocyte helper 2 (Th2) cells involved in the development of allergic diseases." (PMID 34210330, 2021). "It has previously been shown that children protected from the development of (respiratory) allergy have already, at birth, high levels/production of Th1 related cytokines, including IFNG." (PMID 31111043, 2019).
Allergy (continued). "Using peripheral blood T-cells, it has been shown that a PI3Kδ selective inhibitor inhibits TCR stimulated IFNγ and IL-17 production from healthy subjects, and IL-5 and IL-13 production from patients with allergy." (PMID 27716212, 2016). "Reduced mitogen- and allergen-induced IFNγ secretion in CBMCs has been reported in children who subsequently developed allergy." (PMID 20193059, 2010). "Protection against allergy in offspring has also been reported after injection of mothers with the Th1 cytokine IFNγ during pregnancy." (PMID 20193059, 2010). "This resulted in a module that comprised 37 genes, several of which had key roles in allergic disease, for example IFNG and IL4R." (PMID 19216740, 2009). "Although mono-colonization with both EcN-Ctrl and EcN-Chim reduced allergy in poly-sensitized mice, only the mono-colonization with EcN-Ctrl triggered the increased expression of IL-10 (P < 0.01), Foxp3 (P < 0.001), and IFNγ (P < 0.0001) mRNA in the lung as compared to GF poly-sensitized control." (PMID 33679699, 2020). "Production of IFNγ was higher after activation among children with persistent allergy." (PMID 30120223, 2018). "However, the cellular source of IFNγ and its role, as well as the exact role of IL-10 in allergy-suppression by TLA still remains to be investigated." (PMID 29123241, 2017). "For instance, in mice with allergen-induced airway hypersensitivity, huang qi injection suppressed the allergic reaction, enhanced interferon-gamma levels (important immune responsive cytokine) and decreased allergen-induced elevations of important allergy related interleukins IL-5 and IL-13." (PMID 29110710, 2017). "In comparison, lower methylation of IFNγ CpG−54, while considered important to suppressing allergic immune responses in some mouse models, also has been observed paradoxically to enhance allergy or airway hyperresponsiveness." (PMID 28424066, 2017). "From a number of studies it seems that interferon-gamma (IFN-γ) might be one of the appropriate candidate-markers for the prediction of BA and allergy." (PMID 20016777, 2009). "However, IFNγ was increased at this time-point in the ES-62 study and this is consistent with what we find in allergy models with respect to both the parent molecule and its SMAs, where their mechanism of action is considered to at least in part reflect a reversal of Th2 polarisation." (PMID 38077318, 2023). "Furthermore, a previous study in patients with birch pollinosis showed that YRC3780 ingestion could relieve allergy symptoms, decreased plasma thymus and activation-regulated chemokines and elevated plasma interferon-gamma levels." (PMID 34349248, 2022). "NOs is stimulated by Th1 cytokines such as interferon-gamma (IFN)-γ and interleukin (IL)-1 which play important roles in intracellular defense against microorganisms while arginase is activated by Th2 related cytokines such as IL-4, IL-5, and IL-13 which are responsible for allergic reactions." (PMID 30619275, 2018). "Finally, assume that the genetic variation in subject P3 affects IFNγ signaling (which could be the case in some auto-immune disorders like allergy)." (PMID 18783599, 2008). "Already during the perinatal period there are immunological differences in neonates at high risk of allergy, namely relatively reduced capacity for type 1 (Th1) interferon gamma (IFN-γ) responses, compared with low risk neonates with no family history of allergy." (PMID 16551363, 2006). "The pollution decreases the expression of interferon gamma (IFNG) by methylation, leading to the development of Th2 dependent allergic reactions." (PMID 37367080, 2023). "IFNG and IL4 are involved in immune responses, including allergies and antibacterial responses." (PMID 36658343, 2024). "Overall, T cell responses from peanut allergics showed a higher IL-5:IFNγ ratio compared to non-allergics, consistent with studies in other allergy systems." (PMID 30304054, 2018).
Allergy (continued). "Although the actual mechanism is unknown, postulated mechanisms include the involvement of interferon gamma signaling and TH1 immune responses after vaccination, molecular mimicry, PEG-facilitated immune responses, and allergies, as well as the interaction between the SAR-CoV-2 S protein and ACE2." (PMID 36298637, 2022). "The majority of studies conducted so far have confirmed that oral administration of polysaccharides, mainly beta-glucans isolated from Basidiomycetes, may prevent allergies by decreasing the level of immunoglobulin class E (IgE) and increasing the production of IFN-γ (interferon-gamma)." (PMID 34836215, 2021). "Also, unlike with our allergy models where increasing IFNγ offers protection against disease, our data in the current study do not offer definitive evidence on whether the cytokine has protective or pathological (or both) roles in the lungs." (PMID 38077318, 2023).